IL1B (interleukin 1 beta)
Diseases named in the same sentence as IL1B in open-access papers (continued):
Sharing a sentence is not in itself a finding about the gene and the disease.
atherosclerosis (continued). "Previous studies revealed that elevated levels of TNF-α and IL-1β in patients with CVD have been detected, indicating that TNF-α and IL-1β are two important cytokines in vascular inflammation and highly associated with atherosclerosis." (PMID 23895132, 2013). "IL-1B was a proinflammatory cytokine with pleiotropic effects implicated in the various stages of atherosclerosis." (PMID 23762142, 2013). "IL-1β blockade provides a potential therapeutic opportunity to limit atherosclerosis, associated neuroinflammation, and hence cerebrovascular disease such as stroke and vascular dementia." (PMID 23130147, 2012). "To investigate if this is also the case for other chemokines implicated in atherosclerosis and to explore the mechanism, we used IL-1β-stimulated HUVECs pretreated with increasing doses of atorvastatin." (PMID 22815786, 2012). "The IL-1 signaling pathway has been associated with the development of atherosclerosis in animal studies, and IL-1B mRNA is increased in human atherosclerotic arteries." (PMID 22768033, 2012). "Interleukin-1B (IL-1B) is a key pro-inflammatory cytokine that has been associated with the development of atherosclerosis and myocardial infarction." (PMID 22768033, 2012). "Conversely, atherosclerosis-prone mice that were deficient in IL-1β had significantly smaller atherosclerotic plaques." (PMID 22022522, 2011). "In mouse models of atherosclerosis IL-1ra inhibits the formation of intimal fatty streaks in apolipoprotein E-deficient mice, and IL-1β deficient mice when crossed onto an apo e-/- background have reduced atherosclerosis." (PMID 18298837, 2008). "IL1B encodes interleukin-1β, a master regulator of inflammatory responses in atherosclerosis." (PMID 41544081, 2026). "Clinical evidence has linked IL-1β with atherosclerosis through activation of macrophages." (PMID 41066194, 2025). "IL-1β, a key pro-inflammatory cytokine implicated in atherosclerosis progression and plaque formation, was widely expressed in the aortic arch of both MerTKflox/flox mice and MerTKflox/floxTie2Cre mice but was predominantly localized to the endothelium of MerTKflox/floxTie2Cre mice." (PMID 40953531, 2025). "IL-1β activates the pro-inflammatory NF-κB pathway, leading to the production of additional pro-inflammatory cytokines and acute-phase proteins, which are implicated in atherosclerosis and AMI." (PMID 40612273, 2025). "They then generated apoE-deficient mice with myeloid-specific inactivation of IL-10 and demonstrated that these mice exhibit a pro-inflammatory state, with significantly increased expression of TNF-ɑ, and CCL2, a chemokine linked to atherosclerosis as well as a trend toward increased IL-1β." (PMID 39062180, 2024). "Additionally, OxLDL can activate the NLRP3 inflammasome in macrophages, leading to the production of IL-1β and IL-18, cytokines that play key roles in promoting inflammation and have been implicated in the pathogenesis of atherosclerosis." (PMID 39518939, 2024). "In addition, it is known in experimental models that myeloid TET2 deficiency is associated with increased IL-1β production, and with enhanced atherosclerosis development." (PMID 39515317, 2024). "Elevated IL-1β levels are associated with adverse outcomes in coronary artery disease and heart failure, highlighting its role in both the initiation and progression of atherosclerosis." (PMID 39057626, 2024). "Recent research reported in the NEJM that canakinumab targeting IL-1β could reduce the risk of cardiovascular events caused by atherosclerosis, which indicated the important role of inflammation in atherosclerosis." (PMID 36771313, 2023). "We speculate that the expression intensity of IL-1β might be closely related to the progression of atherosclerosis caused by smoking." (PMID 36791122, 2023).
atherosclerosis (continued). "Specifically, some studies have pointed out that CRP might play a role as prognostic marker, and others have indicated that the IL-6 and IL-1β have a causal role in the pathogenesis of atherosclerosis." (PMID 36768804, 2023). "The difference in aortic plaque size between the Tet2-deficient mice and control mice was abrogated by use of an NLRP3 inhibitor, identifying a key role for NLRP3-mediated IL-1β overproduction in promoting atherosclerosis in those harboring TET2 CHIP mutations." (PMID 35122117, 2022). "Also, the major DAMPs including HMGB1 and S100B and their downstream signaling via TLR4 receptor have been intimately associated with the aggravated atherosclerosis resulting in the upregulation of proinflammatory cytokines including IL-18 and IL-1β." (PMID 35531433, 2022). "Moreover, RNA sequencing of cells with loss-of-function mutations in TET2 showed augmented expression of pro-inflammatory mediators implicated in the pathogenesis of atherosclerosis including IL-1β and IL-6." (PMID 35657494, 2022). "Genes involved in fluid shear stress and atherosclerosis include IL1β, TNF, MMP9, AKT1, and NOX4; genes associated with AGE-RAGE signaling pathway in diabetic complications include AKT1, IL1β, and NOX4; while genes associated with HIF signaling pathway contain STAT3, NOX4, NFκB, and MAPK1." (PMID 36192741, 2022). "Indeed, research has shown that higher levels of both CRP and IL-1β are associated with atherosclerosis in the brain, reduced white matter fractional anisotropy (i.e., microstructural integrity), and impaired synaptic plasticity and neurogenesis." (PMID 36612568, 2022). "IL-1β deficiency or IL-1β blockers can improve atherosclerosis in mice." (PMID 35656105, 2022). "Pyroptosis is a new form of programmed cell death generated by some inflammasomes, piloting the cleavage of gasdermin (GSDM) and stimulation of dormant cytokines like IL‐18 and IL‐1β; these reactions are narrowly linked to certain diseases like diabetic nephropathy and atherosclerosis." (PMID 34369076, 2021). "The results of the Canakinumab Anti‐Inflammatory Thrombosis Outcome Study (CANTOS) confirmed the role of vascular inflammation and IL‐β in atherosclerosis by demonstrating that the risk of recurrent cardiovascular events can be reduced with an IL‐1β‐neutralising antibody." (PMID 34377468, 2021). "IL-1β was one of the first cytokines implicated in the pathogenesis of atherosclerosis." (PMID 34210954, 2021). "The results of in vitro cell-based assays that H5 upregulate the expression of atherogenic IL-1β/IL-8 and enhance the foam cell formation suggest that H5 may contribute to RA-associated atherosclerosis." (PMID 34768851, 2021). "In addition to RA, the pathogenic involvement of IL‐1β in animal models of atherosclerosis is well documented." (PMID 33204425, 2020). "It has been clearly shown that, in the atherosclerotic plaque, endocytosed LDL release cholesterol that upon crystallization may activate the NLRP3 inflammasome, resulting in the release of mature IL-1β and IL-18, associated with augmented atherosclerosis." (PMID 32585928, 2020). "Interestingly, HoxB9 negatively regulates the expression of IL-1β which can have both protective and pathogenic effects in atherosclerosis." (PMID 31504243, 2020). "Moreover, the increased susceptibility of atherosclerosis associated with the presence of clonal hematopoiesis in peripheral-blood cells was regulated at least in part by the NLRP3/IL-1β pathway." (PMID 33362770, 2020).
atherosclerosis (continued). "The complement system detects viral pathogens, thus contributing to the innate immune response to viral infections, whilst NETs have the ability to induce IL-1β secretion from macrophages and play a role in the development of atherosclerosis, causing endothelial damage and dysfunction." (PMID 33363221, 2020). "The CANTOS clinical trial (2017) has provided evidence that in patients with elevated inflammation (hsCRP > 2 mg/L), a combination therapy of statins and canakinumab (IL-1β antibody) may be necessary to lower atherosclerosis risk." (PMID 32317975, 2020). "Furthermore, experimental and human atherosclerotic plaques contain IL-1β and its loss of function limits experimental atherosclerosis." (PMID 31779200, 2019). "Moreover, recent studies showed that accumulation of free cholesterol in macrophages leading to activation of NLRP3 inflammasome and production of interleukin-1β (IL-1β) has been linked to atherosclerosis-associated inflammation." (PMID 30983887, 2019). "Long-term (3.7 year) follow-up of the randomized phase 3 CANTOS trial of the anti-IL-1β antibody canakinumab in patients with atherosclerosis, prior MI, and high CRP level found a 77% reduction in risk of LC death relative to placebo in the canakinumab arm (HR 0.23; P = 0.0002)." (PMID 30279971, 2018). "Two recent studies investigating the role of clonal expansion of hematopoietic cells as a potential driver for age-related onset of atherosclerosis have provided evidence that IL1β secretion from TET2 deficient macrophages plays a role in the acceleration of disease." (PMID 29988570, 2018). "This suggests that the development of atherosclerosis mediated by P2X7R in mice may be associated with the modulation of IL-1β activation and release." (PMID 25761252, 2015). "Interestingly, GM-CSF signaling significantly increases IL-1β secretion and IL-1β is implicated in atherosclerosis in animal studies." (PMID 24995121, 2014). "Single-nucleotide polymorphisms of IL-1β, which may elevate circulating IL-1β, are frequently observed in patients with metabolic syndrome including atherosclerosis and NASH." (PMID 21274430, 2010). "Furthermore, modulating IL-4, TNF-α, and IL-1β expression suggests an immunomodulatory effect that could reduce atherosclerosis risk." (PMID 40630842, 2025). "In atherosclerosis, anti-inflammatory treatment could also modify the progression of the disease, as shown in recently completed trials that demonstrated the efficacy of IL-1β inhibition on the reduction of cardiovascular risk." (PMID 34205487, 2021). "In humans, the CANTOS trial of the anti-IL-1β blocking antibody canakinumab in patients with a history of myocardial infarction and elevated serum hsCRP (high-sensitivity C-reactive protein) demonstrates that inflammation is a direct cause of the onset and development of atherosclerosis." (PMID 31653058, 2019). "In addition, a recent study established a causal link between NLRP3-mediated overproduction of IL-1β and the development of atherosclerosis in a ten-eleven translocation 2 (TET2) mutant mouse model, which could be abrogated by an NLRP3 inflammasome inhibitor." (PMID 30279971, 2018). "Thus, in ApoE−/− mice deficiency of IL-1β decreased the extent of atherosclerosis." (PMID 24244322, 2013). "Inflammatory mediators such as IL-6, TNF-α, and IL-1β play a crucial role in cardiovascular disease, particularly in the pathogenesis of atherosclerosis, endothelial dysfunction, and CVD." (PMID 41601490, 2026). "Studies have shown that IL-1β can accelerate the progression of atherosclerosis by inducing lesions in vascular smooth muscle cells through upregulation of P2Y receptors." (PMID 41601490, 2026).
atherosclerosis (continued). "IL-1β is a key cytokine in autoinflammation, driving inflammation, atherosclerosis, cartilage and bone destruction in inflammatory diseases." (PMID 41550415, 2026). "miP-PSTPIP2 expression was upregulated in IL-1β-treated human endothelial cells, in pre-atherosclerotic murine carotid arteries and detected in carotid arteries from patients with atherosclerosis." (PMID 42156223, 2026). "We therefore consider NLRP3 a promising therapeutic target in atherosclerosis, as it combines classic inflammasome inhibition—reducing IL-1β and IL-18 release—with direct anti-proliferative effects on plaque macrophages." (PMID 40956333, 2025). "In conclusion, this study found that the important direct targets of hawthorn in atherosclerosis included IL1B, CTSD, HMOX1, and PPARG." (PMID 40824771, 2025). "TNFα and IL-1β, which are abundant in advanced atherosclerosis, can promote ADAM17-dependent proteolytic cleavage of MerTK, substantially disabling efferocytosis​." (PMID 40172727, 2025). "Pro-inflammatory cytokines, such as TNF-α and IL-1β, contribute to atherosclerosis by inducing the expression of E-selectin, intercellular adhesion molecule 1 (ICAM-1), and vascular cell adhesion molecule 1 (VCAM-1) in endothelial cells." (PMID 41155632, 2025). "Numerous studies have reported that IL-1β is involved in both the onset and the progression of atherosclerosis; however, randomized clinical trials have confirmed its therapeutic relevance only in the last decade." (PMID 41272654, 2025). "Further studies indicate that macrophages modulate vSMC function during atherosclerosis progression through IL-1β, whereby macrophage-derived IL-1β influences vSMC phenotype." (PMID 40172727, 2025). "Anti-inflammation is increasingly recognized as a promising approach to atherosclerosis prevention, with agents such as canakinumab (IL-1β inhibitor) and sodium-glucose co-transporter-2 inhibitors, though their anti-inflammatory effects 89-92." (PMID 40303308, 2025). "Elevated IL-6, TNF-α, and IL-1β levels in HIVwt-infected mice support inflammation as the main mechanism behind Nef-dependent atherogenesis, consistent with the view of atherosclerosis as a chronic inflammatory disease." (PMID 40237461, 2025). "Its activation and subsequent IL-1β release are observed beginning in early-stage atherosclerosis and continue to sustain a pro-inflammatory environment throughout disease development." (PMID 41282617, 2025). "Targeting IL-1β or IL-1Ra could represent an effective therapeutic strategy for addressing the inflammatory processes in ischemic stroke, both during the acute phase and as part of the chronic conditions that contribute to atherosclerosis and increase the risk of stroke." (PMID 41301455, 2025). "IL-1β, TNF-α and MCP-1 are inflammatory factors closely associated with the development of atherosclerosis." (PMID 40076117, 2025). "Another study in animal models reported that pharmacological inhibition of NLRP3 inflammasome in TET2-deficient mice resulted in decreasing the inflammatory state, lowering IL-1β, and ameliorating atherosclerosis and heart failure." (PMID 40804878, 2025). "Recent research has highlighted the critical role of IL-1β in the initiation and progression of arterial calcification in atherosclerosis." (PMID 40241989, 2025). "NLRP3 inflammasome-mediated activation of IL-1β secretion has become an important component of the inflammatory process in atherosclerosis." (PMID 40867876, 2025). "Studies involving animal models have demonstrated that IL-1β inhibition impedes the progression of atherosclerosis." (PMID 41303445, 2025). "Activated in renal myeloid cells → ↑ IL-1β → amplifies inflammation and accelerates atherosclerosis." (PMID 41154568, 2025). "Given the key role of inflammation in atherosclerosis, we performed immunostaining to assess the expression of inflammatory markers IL-1β, MCP-1, NF-κB, TNF-α, IFN-γ." (PMID 40953531, 2025).
atherosclerosis (continued). "As a key proinflammatory factor in CHD, IL-1β promotes atherosclerosis formation and plaque instability through multiple mechanisms." (PMID 41287052, 2025). "The CANTOS, which demonstrated that IL-1β inhibition significantly reduces cardiovascular events, highlights the potential for targeting inflammatory pathways in atherosclerosis treatment." (PMID 40217801, 2025). "The resulting M1 macrophages promote inflammatory responses through abundant secretion of growth factors and cytokines, particularly TNF-α and IL-1β - two central mediators of atherosclerosis-related inflammatory pathways." (PMID 41268564, 2025). "TET2 deletion promotes the occurrence of cardiovascular disorders such as cardiac failure and atherosclerosis by the activation of IL‐1β/NLRP3 inflammasome through macrophages." (PMID 40607626, 2025). "Inflammatory cytokines IL-1b and IL-6 appear to play a central role in mediating inflammation and subsequently atherosclerosis (i.e. the inflammasome/IL-1/IL‐6 pathway)." (PMID 39988580, 2025). "The ADAM family, especially ADAM10 and ADAM17, has been implicated in the shedding of pro-inflammatory cytokines, such as tumour necrosis factor-alpha (TNF-α) and interleukin-1 beta (IL-1β), which exacerbate the inflammatory response in atherosclerosis." (PMID 40492135, 2025). "Key search terms used included “atherosclerosis”, “inflammation”, “biological therapy”, “IL-1β inhibitors”, “IL-6 inhibitors”, and “TNF-α inhibitors”." (PMID 40727466, 2025). "The CANTOS trial provides strong support for the significance of IL‐1β in atherosclerosis, as therapeutic IL‐1β neutralization in patients with established atherosclerotic disease significantly reduces the incidence of recurrent cardiovascular events." (PMID 39158380, 2025). "To this end, we used a variety of Medical Subject Headings (MeSHs) and free-text keywords, including “inflammasome”, “NLRP3”, “cardiovascular diseases”, “atherosclerosis”, “heart failure”, “pericarditis”, “pyroptosis”, “IL-1β”, “IL-18”, and “targeted therapy”." (PMID 40564905, 2025). "The activation of NLRP3 in endothelial cells (ECs) represents a key event leading to endothelial damage, and its impact on atherosclerosis is primarily mediated by the effector cytokine IL-1β." (PMID 41194915, 2025). "Pro-inflammatory pathways, including IL-1β/IL-6 signaling, NLRP3 inflammasome activation, and JAK2-mediated thrombo-inflammation, explain its role in atherosclerosis, metabolic dysfunction, and thrombotic risk, highlighting druggable targets for prevention." (PMID 41516113, 2025). "Our results demonstrate that GC potentiates CMA activity in macrophages, leading to promoted degradation of the NLRP3 inflammasome, suppression of NLRP3/IL-1β-mediated inflammation, and ultimately conferring protection against atherosclerosis." (PMID 41282617, 2025). "CYBB, HMOX1, IL1B, TYROBP, and CSF1R are key genes associated with ferroptosis, a form of cell death triggered by lipid metabolism abnormalities in the context of atherosclerosis." (PMID 40895546, 2025). "Activation of NLRP3 induces IL-1β release, a key driver of both atherosclerosis and heart failure with mildly reduced ejection fraction (HFmrEF)." (PMID 41573444, 2025). "Secondly, TCAs suppress cytokine production, including pro-inflammatory cytokines such as TNF-α, IL-1β, and IL-6, which are key mediators in the pathogenesis of atherosclerosis." (PMID 40006011, 2025). "The CANTOS (Canakinumab Anti-Inflammatory Thrombosis Outcomes Study) trial investigated the relationship between inflammation and atherosclerosis comparing canakinumab, an interleukin-1β (IL-1β) inhibitor, versus placebo." (PMID 41375637, 2025).